NMU (neuromedin U)
Diseases named in the same sentence as NMU in open-access papers (continued):
Sharing a sentence is not in itself a finding about the gene and the disease.
parasitic infection (1 paper, 2024). "Recent studies have shown that NMUR1 is expressed on ILC2s membrane in the lamina propria of the small intestine, and the expression of NMU can be significantly increased when M. benedeni infected, and ILC2s can be effectively activated by NMUR1 and act as the anti-parasitic infection functions." (PMID 38956647, 2024).
Sepsis (1 paper, 2021). Sepsis is defined as life-threatening organ dysfunction caused by a dysregulated host response to infection. "The results show that sepsis markedly increased the expressions of nmu mRNA by ~2.4-fold and NMU protein by ~2.1-fold in the lungs." (PMID 33995408, 2021).
tobacco use disorder (1 paper, 2020). "Peptides that regulate appetite such as glucagon-like peptide 1 (GLP-1), ghrelin, leptin, peptide YY, and neuromedin U are expressed throughout the brain reward circuitry, providing strong evidence that food addiction and tobacco use disorder share overlapping gut–brain axis mechanisms." (PMID 33334010, 2020).
tumor (15 papers, 2011 to 2025). "NMU and EREG encode for Neuromedin U and Epiregulin, respectively, both of which are involved in tumor invasion and progression." (PMID 36868311, 2023). "NMU (Neuromedin U) is a neuropeptide that has been implicated in energy homeostasis and tumour progression." (PMID 21791076, 2011). "NmU, a neuropeptide known for its role in immune response and regulation of smooth muscle contraction, appears to promote tumor growth and metastasis in PDAC." (PMID 39869563, 2025). "Among them, the expression of CNR2, GIP, GNGT1, NPY1R, SSTR5, and LEP in tumor tissue was significantly lower than in normal tissue, while the expression of GPSM2, and NMU was significantly highly expressed in tumor tissue." (PMID 33169793, 2020). "The upregulation of NmU in PDAC tissues correlates with more aggressive tumor behavior, suggesting that NmU-targeted therapies could offer new avenues for treating PDAC, particularly in cases where NmU expression is high." (PMID 39869563, 2025). "Therefore, this study focuses on the relationship between estrogen-related genes (ERGs) expression and prognosis in PTC, particularly neuropeptide U (NMU), and its important role in tumor progression." (PMID 36917092, 2023). "In other cancers, high cytoplasmic NMU protein expression is present in tumor cells." (PMID 32013887, 2020). "YAP1 upregulates NMU expression and promotes tumor metastasis." (PMID 31575084, 2019). "Our prognostic signature include four genes, SERPINE2, SNCAIP, NMU, and S100A9, each playing a critical role in tumor progression, invasion, and metastasis." (PMID 37691944, 2023). "Immunohistochemical staining showed that NMU protein was present in intercellular space of HCC peri- and intra-tumor tissue, rather in hepatic cells or HCC cells." (PMID 32013887, 2020). "NMU and NTS receptors, which belong to G-protein-coupled receptor (GPCR) families, were found to be expressed on the membrane of immune cells including T cells, B cells, macrophages, dendritic cells, mast cells, and on tumour cells." (PMID 34141479, 2021). "NMU was highly expressed in both tumor tissue and normal tissue, and NPY1R and SSTR5 were not collected in the HPA database." (PMID 33169793, 2020). "However, we also noticed that knockdown of NMU in Ishikawa cell line, from the grade I cancer, did not change various tumor progression-related events, suggesting that the involvement of NMU signaling in endometrial tumorigenesis might be heterogeneous and depend on the cancer stages." (PMID 26849234, 2016).
cancer (14 papers, 2015 to 2025). A tumor composed of atypical neoplastic, often pleomorphic cells that invade other tissues. "Taken together, these results suggest that high NMUR2 and NMU expression correlates with decreased cancer differentiation and increased invasive potential." (PMID 34493299, 2021). "This screening system identified 25 genes correlated with YAP1 expression in the cancer group, among which we selected NMU as the most significantly overexpressed gene in patient samples and cancer cell lines." (PMID 31575084, 2019). "Additionally, neuromedin U (NmU) has been implicated in PDAC pathogenesis, providing novel insights into its role in cancer biology." (PMID 39869563, 2025). "Neuromedin U (NMU), a neuropeptide isolated from porcine spinal cord and named because of its activity as a rat uterus smooth muscle contraction inducer, is emerging as a new player in the tumorigenesis and/or metastasis of many types of cancers." (PMID 31492042, 2019). "Neuromedin U (NMU), a small secreted peptide, has a myriad of different functions and recently became a point of interest in cancer studies." (PMID 36482448, 2022). "Accumulating evidence shows that the aberrant expression of neuromedin U (NMU) contributes to the initiation and progression of cancer." (PMID 34336003, 2021). "Neuromedin U (NMU) is a secretory neuropeptide that was first isolated from the porcine spinal cord, and it has emerged as a novel factor involved in the tumorigenesis and/or metastasis of many types of cancers." (PMID 34493299, 2021). "Our CRC cell clone studies showed that regardless of the parental cell phenotype, NMU overexpression in cells expressing NMUR2 enhances the metastatic potential of the cells by increasing their mobility and invasiveness via ERK1/2 kinase activation, as previously shown for other cancers." (PMID 34493299, 2021).
metabolic disorders (4 papers, 2021 to 2025). "Neuromedin U (NMU) is a neuropeptide expressed in several peripheral tissues that could be considered a potential bridge between metabolic disorders and inflammation and a good candidate as a biomarker in CVD risk assessment." (PMID 40868161, 2025).
infection (1 paper, 2018). The state of being infected such as from the introduction of a foreign agent such as serum, vaccine, antigenic substance or organism. "Some notable exceptions exist, such as pioneering work demonstrating nerve–mast cell interaction following infection with parasitic nematodes and the recent finding that neuromedin U influences the function of innate lymphoid cells (ILCs) in the context of infection with nematodes." (PMID 30177522, 2018).
NMU also shares sentences with these, for which no sentence is quoted: renal carcinoma (2 papers); type 2 diabetes (2); adenoma (1); glioblastoma (1); Hyperglycemia (1); lung squamous cell carcinoma (1); melanoma (1); nervous system disease (1); non-small cell lung carcinoma (1); osteosarcoma (1); psychiatric disorder (1); small cell lung carcinoma (1).